HIF1A (hypoxia inducible factor 1 subunit alpha)
Diseases named in the same sentence as HIF1A in open-access papers (continued):
Sharing a sentence is not in itself a finding about the gene and the disease.
tumor (continued). "Additionally, MPT0B098, a microtubule inhibitor, significantly reduces HuR translocation from the nucleus to the cytoplasm in various tumor cells, leading to decreased hypoxia-inducible factor 1-α (HIF-1-α) protein expression." (PMID 39849491, 2025). "HIF-1α is a key regulator of the tumor hypoxic environment, promoting tumor survival, and may serve as a potential therapeutic target." (PMID 40546546, 2025). "The high expression of HIF1A indicates that the tumor environment is in a state of hypoxia." (PMID 40552073, 2025). "Therefore, enhancing our understanding of the role of HIF-1α in tumor metastasis, especially under hypoxic stress, is imperative to improve the potential clinical value of HIF-1α target." (PMID 40164945, 2025). "Therefore, HIF-1α plays a key role in the metabolic reprogramming of tumor cells, helping them adapt to the harsh hypoxic environment and sustain their proliferative capacity." (PMID 40443737, 2025). "The activation of HIF-1α can induce tumor cells to exhibit endothelial-like characteristics." (PMID 41019994, 2025). "Importantly, the WWOX/HIF1A ratio not only reflects tumour metabolic states but also integrates signals from the TME, including ECM remodelling and immune responses, which further influence tumour progression and therapeutic resistance." (PMID 41007296, 2025). "Alongside this, targeting HIF-1α through inhibitors may increase the anti-tumor effect, thereby reducing the resistance to conventional cancer treatment strategies and halting the progression." (PMID 39996906, 2025). "In addition, glycolytic metabolism helps to regulate the recruitment of MDSCs in the microenvironment before metastasis, and increased numbers of MDSCs, in turn, are likely to facilitate the metastasis of tumor cells to the liver through HIF‐1α signaling." (PMID 40452814, 2025). "A strong correlation was found only between the level of HIF-1α and the size of the tumor." (PMID 40429943, 2025). "Second, many studies suggested that HIF1A acts as a tumor suppressor, so its reduced activity in relation to surrounding healthy tissue could contribute to the initiation of tumor development in the kidney, a finding consistent with our data." (PMID 40332447, 2025). "Therefore, VC supplement can enhance HIF hydroxylase function, thereby reducing HIF-1α expression and inhibiting tumor progression." (PMID 40950984, 2025). "Importantly, the stiffer core region was correlated to higher HIF-1α expression, replicating a key feature of the tumour microenvironment." (PMID 40422376, 2025). "A high WWOX/HIF1A ratio is linked to dysregulation of DNA repair mechanisms, including DNA replication, nucleotide excision repair (NER), and base excision repair (BER), leading to increased mutations and tumour progression due to low WWOX expression." (PMID 41007296, 2025). "On the other hand, HIF-1α is associated with plasticity of Th1, Th17 and Treg cells toward Th17-like phenotype, suggesting that HIF-1α plays an important role in tumor progression and T cell immune response modulation by induction of inflammatory T cell phenotypes." (PMID 40963621, 2025). "For example, targeting HIF-1α alongside VEGF inhibition may normalize tumor vasculature, improving immune cell infiltration and therapy delivery." (PMID 39981236, 2025). "Additionally, in pancreatic neuroendocrine tumors, the increase in 24S‐hydroxycholesterol, induced by hypoxia‐inducible factor‐1α (HIF1α), attracts neutrophils to the tumor microenvironment, promoting angiogenesis." (PMID 40145543, 2025). "The detection of HIF-1α and HIF-2α in tumor biopsies or CTCs may serve as indicators of tumor aggressiveness and metastasis risk." (PMID 40901111, 2025). "And blocking the PD-1 signal can promote the HIF-1α signaling pathway in tumor cells." (PMID 40825269, 2025). "Given the importance of HIF-1α in aerobic glycolysis, we hypothesized that ONECUT3 might regulate tumor glycolytic metabolism through HIF-1α." (PMID 40032849, 2025).
tumor (continued). "Nuclear HIF-1α expression in tumor cells was quantified, with >1% considered positive." (PMID 39857068, 2025). "Moreover, hypoxic conditions in the tumor microenvironment upregulate IL-6 secretion by CAFs via HIF-1α-dependent mechanisms, promoting CRC cell proliferation and survival." (PMID 40718440, 2025). "Lactic acid can also promote M2-like polarization of tumor-associated macrophages (TAMs) by regulating the ERK/STAT3 signaling pathway, and induce myeloid-derived suppressor cells (MDSCs) through the regulation of HIF-1α." (PMID 41236698, 2025). "HIF-1α expression was closely correlated with the oxygenation status of tumor and could serve as an important biomarker for tumor hypoxia, aggressiveness, or radiation resistance." (PMID 40444079, 2025). "In addition to its role in tumor tissues, lactate can trigger osteoblast differentiation and induce fibroblast metabolic reprogramming by stabilizing HIF-1α." (PMID 40760493, 2025). "Additionally, interfering with the HIF1α-platelet-derived growth factor D (PDGFD)-PDGF-receptor α (PDGRα)-AKT impairs the feedforward loop of HIF1α perpetuation in the hypoxic tumor core." (PMID 39859381, 2025). "Recent studies indicate that HIF-1α promotes tumor cell survival by inhibiting ferroptosis." (PMID 41154694, 2025). "However, in hypoxic tumor cells, HIF-1α stability is enhanced through SIRT5-mediated desuccination of PPA2." (PMID 40164945, 2025). "Multiple studies reported that HIF1A may function as a tumor suppressor gene, whereas EPAS1 acts as an oncogene." (PMID 39477683, 2025). "Furthermore, curcumin exerts multidimensional therapeutic effects by targeting the hypoxia-HIF-1α signaling pathway, thereby inhibiting tumor metabolic adaptation, blocking invasion and metastasis, and enhancing chemosensitivity." (PMID 41515171, 2025). "In tumor tissue, HIF-1α is closely related to tumor progression." (PMID 40420185, 2025). "As a result of the in situ oxygen synthesis, hypoxia in the tumor microenvironment may be significantly eased, reducing the expression of HIF-1α, inhibiting tumor growth, angiogenesis, and metastasis." (PMID 40468341, 2025). "Moreover, it was shown that treating DU145 and A2058 tumor cells with a STAT3 inhibitor led to a reduction in HIF-1α." (PMID 40408503, 2025). "This oxidative stress stabilizes HIF-1α, supporting tumor growth." (PMID 40931345, 2025). "Additionally, lactic acid promotes the polarization of tumor-associated macrophages toward the M2 phenotype, driving malignant tumor progression via the lactate–MCT HIF1α signaling pathway." (PMID 40723225, 2025). "Ankrd37 (ankyrin repeat domain 37) gene expression could be activated under hypoxia via the Hif-1a-dependent pathway, affecting autophagy, cell survival, and tumor progression." (PMID 41009560, 2025). "Additionally, genes like AAED1 are involved in HIF-1α-mediated glycolytic activation under hypoxia, supporting tumor cell proliferation and survival." (PMID 41220952, 2025). "The hypoxic response could serve as a prognostic marker and therapeutic target for instance, via imaging with hypoxia tracers or by immunohistochemistry for CA9/HIF-1α in tumor biopsies." (PMID 41174561, 2025). "Interestingly, the expression of these proteins was also detected in healthy tissue, indicating that the tumor microenvironment and HIF1A status play a crucial role in modulating their expression." (PMID 40332447, 2025). "Given the multiple pro-tumor mechanisms of HIF-1α activation, it becomes essential to determine whether these preclinical concerns translate into clinical risk." (PMID 41311849, 2025).
tumor (continued). "Moreover, we observed that HIF1A upregulation enhances hypoxic adaptation and vascular remodelling, further compounding the invasive potential of these tumours." (PMID 41007296, 2025). "HIF-1α, a critical regulator of cellular responses to hypoxia, is often overexpressed in cancer due to genetic alterations such as gain-of-function mutations in oncogenes such as the KRAS mutation and loss-of-function mutations in tumor suppressor genes." (PMID 39996842, 2025). "These exosomes enforce non-polarized macrophages to acquire the tumor-associated macrophages phenotype through HIF-1α and HIF-2α regulated SOCS4/SOCS5/STAT3 signaling pathway." (PMID 39928285, 2025). "At the same time, the expression of HIF-1α can also regulate the apoptosis of tumor cells, which complicates the structural components of tumor tissue, which is another reason for the increase of MK in EC patients with high expression of HIF-1α." (PMID 40444079, 2025). "However, preclinical studies demonstrate HIF-1α activation promotes tumor progression via multiple pathways (metabolic reprogramming, angiogenesis, metastasis, apoptosis resistance, immune evasion, chemoresistance)." (PMID 41311849, 2025). "Although concerns were raised that elevated HIF-1α levels might facilitate tumor growth via VEGF upregulation, the activation of the tumor immune response mitigated this risk, resulting in tumor growth inhibition." (PMID 40343532, 2025). "Therefore, PI3K/AKT pathway facilitates calcification and enhances HIF1α expression, hence supporting tumor proliferation and medication resistance." (PMID 40740483, 2025). "In addition, it has been reported that Ndrg1 is directly or indirectly regulated by HIF-1α in an oxygen-dependent manner, thereby affecting cancer metabolism and tumor progression." (PMID 40484376, 2025). "UBE2CP3 has been shown to promote hepatocyte VEGFA secretion into the tumor microenvironment and enhance tumor cell-induced angiogenesis through activation of the ERK/p70S6K/HIF-1α pathway, while ERK signaling has previously been noted to play a role in the regulation of tumor EMT." (PMID 40028033, 2025). "ATP citrate lyase (ACLY), a target of HIF-1α, is upregulated in hypoxic tumor cells." (PMID 40813760, 2025). "HIF-1α is positively correlated with VEGF, and HIF-1α may promote tumor angiogenesis and tumor cell metastasis by up-regulating VEGF." (PMID 40309242, 2025). "HIF-1α, in particular, has been shown to promote the expression of immune-related genes, including those involved in immune cell recruitment and the suppression of anti-tumor immune responses." (PMID 40901111, 2025). "The development of nanoparticle (NP)-based delivery systems for precision targeting of HIF-1α inhibitors to LN-resident macrophages may represent a promising therapeutic strategy to enhance T cell tumor infiltration and overcome resistance to ICIs." (PMID 41281945, 2025). "In the cytoplasm, the inhibition of PHDs by tumor metabolites activates and stabilizes HIF-1α." (PMID 41551149, 2025). "HIF-1α is primarily activated in a hypoxic tumor microenvironment." (PMID 40507893, 2025). "Other findings reflective of CS1’s higher tumor grade and more aggressive behavior compared with CDS11 cells include the significantly higher mRNA levels of INSULINR, IGF2R, IRS1, NOTCH1, JAGGED1, HES1, and HIF1α, which function to promote tumor cell growth and survival." (PMID 40427168, 2025). "In pancreatic cancer, the low-sugar and hypoxia microenvironment promotes tumor progression by activating HIF1 α and c-MYC signals, and β-TrCP may indirectly regulate these pathways." (PMID 40534867, 2025). "Notably, BACH1 was shown to regulate angiogenesis both in collaboration with and independently of HIF1α, highlighting its central role in antioxidant-induced tumor progression." (PMID 40646353, 2025).
tumor (continued). "Additionally, systemic anaemia exacerbates hypoxia in the tumour microenvironment, stabilising HIF-1α and further promoting angiogenesis, metabolic adaptation, and tumour aggressiveness." (PMID 41153383, 2025). "HIF-1α plays a critical role in regulating fatty acid uptake and storage within tumor cells." (PMID 41333208, 2025). "This upregulation of HIF1-α reveals that surviving normoxic tumor cells can accumulate HIF-1α, promoting VEGF secretion after doxorubicin treatment and their neo-angiogenesis, which could serve as a survival mechanism." (PMID 40032892, 2025). "This suggests that while NT5E inhibition does not directly impact VEGF production, it may enhance the overall anti-tumor microenvironmental effects of HIF1α inhibition when used in combination." (PMID 41463265, 2025). "Accumulation of HIF-1α was found to be the major driver of adaptation in cancer cells coordinating the mechanisms of the metabolic switch and neutralization of intracellular acidosis and further inducing tumor cell stemness and resistance to apoptosis." (PMID 40362659, 2025). "An interesting result may be the strong positive correlation between HIF-1α and tumor size for samples taken from the tumor mass (homogenates)." (PMID 40429943, 2025). "Subsequently, lactic acid enters vascular endothelial cells through MCT1 and is converted into pyruvate, which activates the HIF-1α and nuclear factor-κB (NF-κB)/interleukin-8 (IL-8) signaling pathways, inducing endothelial cell migration and tumor angiogenesis." (PMID 40034817, 2025). "As a miRNA sponge, circRNA activates the translation of hypoxia-related factors such as HIF1-α through the circRNA-miRNA-mRNA axis, which influences the activity and functionality of immune cells within the tumor microenvironment, thereby potentially fostering the progression of cancer growth." (PMID 40296917, 2025). "SLC16A3 overexpression partially rescued the tumor-suppressive effect of HIF1A knockdown in vivo." (PMID 41293164, 2025). "Because ROS, ER stress, AMPK–mTOR signaling, and HIF-1α pathways are interconnected, these findings support a model in which TQ disrupts hypoxia-driven survival programs while promoting apoptosis or cytotoxic autophagy, depending on tumor context." (PMID 41303508, 2025). "Furthermore, mitochondrial dysfunction induces excessive accumulation of ROS, thereby activating the HIF-1α signaling pathway, which further promotes glycolysis and tumor cell invasion." (PMID 41164182, 2025). "HIF-1α expression was significantly correlated with the grade of the tumour (p = 0.035)." (PMID 41625861, 2025). "Notably in VHL-deficient RCC, there is a pronounced preference for HIF-2α expression, which correlates with enhanced tumor growth, while HIF-1α appears to inhibit tumor proliferation." (PMID 39470609, 2025). "Moreover, TACE induces tumor hypoxia, resulting in the increased expression of hypoxia inducible factor-1α (HIF-1α)." (PMID 40777037, 2025). "Even when oxygen is abundant, tumor cells still maintain high levels of HIF-1α for survival." (PMID 40563539, 2025). "As a response to HIF-1α signaling, cancer cells upregulate glutamine intake and subsequent metabolism by increasing transporters on the plasma membrane, allowing more glutamine into the tumor." (PMID 41450919, 2025). "In contrast to HIF-1α, which may exhibit context-dependent tumor-suppressive effects, HIF-2α functions as a principal oncogenic driver in ccRCC." (PMID 41451091, 2025). "This metabolic symbiosis can occur between hypoxic tumor cells, in which upregulation of HIF-1a promotes glycolysis and lactate production, and oxidative tumor cells, which take up the exported lactate for oxidative phosphorylation and thereby maximum energy gain." (PMID 40350469, 2025). "VEGF plays a crucial role in tumor angiogenesis and is identified as a specific target for HIF-1α." (PMID 40011711, 2025).
tumor (continued). "Additionally, under hypoxic stress, ANXA1 inhibits glycolytic reprogramming mediated by HIF-1α, thereby reducing the sensitivity of tumor cells to rituximab." (PMID 41189944, 2025). "Strategies such as generating oxygen in situ within tumors or inhibiting mitochondrial respiration while targeting the HIF-1α pathway may alleviate tumor hypoxia." (PMID 40169560, 2025). "Thus, while HIF-1α is a central regulator of fructose metabolism in hypoxia, tumor cells can adapt to ensure fructose catabolism (and survival) even when HIF signaling is compromised 28​." (PMID 40520908, 2025). "The transcription factor HIF1α supports tumor growth by promoting angiogenesis in the hypoxic TME." (PMID 40098971, 2025). "Moreover, reduced HIF-1α expression in syngraft tumors moderately downregulated VEGFR1 and 3 and was associated with decreased tumor volume and size." (PMID 41514626, 2025). "On the other hand, in studies conducted on therapy suggest that blocking exosome secretion or cargo loading via HIF1A, Rab27A/B or nSMase2 inhibitors may reduce tumor progression." (PMID 39928285, 2025). "Lin and colleagues were the first to provide evidence for an antitumour role of DUSP2, demonstrating that its expression is markedly diminished or absent in many human cancers, with expression levels inversely correlating with both HIF-1α expression and tumour malignancy." (PMID 40943262, 2025). "The upfront use of TACE in HCC with a high tumor burden may sometimes be incomplete, increasing tumor hypoxia and the upregulation of hypoxia-inducible factor-1α (HIF1α),VEGFs, and PDGFRs." (PMID 40361498, 2025). "To determine whether the anti-tumor effects of Curcumol are mediated via inhibition of HIF-1α signaling, we used dimethyloxalylglycine (DMOG), a prolyl hydroxylase inhibitor that stabilizes HIF-1α." (PMID 41008845, 2025). "Mechanistically, intermittent hypoxia (IH) from OSA promotes tumor aggressiveness through hypoxia-inducible factor-1 alpha (HIF-1α) stabilization, M2 macrophage polarization, and impaired DNA repair, while circadian disruption alters endocrine signaling and immune regulation." (PMID 41357522, 2025). "Collectively, our findings demonstrate that the WWOX/HIF1A ratio critically modulates oncogenic signalling across multiple tumour types, influencing prognosis, therapeutic response, and disease progression through the regulation of key proliferation and survival pathways." (PMID 41007296, 2025). "Furthermore, the adenosine-generating ectoenzymes CD39 and CD73 are regulated by HIF1A and have been shown to promote tumor growth, invasiveness, and metastatic potential, resulting in poor clinical outcomes." (PMID 40125552, 2025). "HIF-1α regulates a key enzyme involved in glycolysis, enabling tumor cells to survive hypoxia." (PMID 40420185, 2025). "In the hypoxic tumor microenvironment, macrophages express PD-L1 in response to HIF-1α secretion." (PMID 40034694, 2025). "HIF‐1α promotes the occurrence, development, and metastasis of tumors by promoting angiogenesis, accelerating metabolic changes, and supporting the survival of tumor cells." (PMID 40944417, 2025). "Furthermore, the accumulation of VBL/MnO2 nanodrugs in tumor tissues via passive targeting resulted in the effective reduction of hypoxia and HIF-1α expression in vivo." (PMID 40893378, 2025). "The samples showed the influence of HIF1α on tumor initiation, growth, invasion, and metastasis." (PMID 40806669, 2025). "Additionally, CA‐4 was able to down‐regulate the HIF‐1α expression, restrain the neovascularization of tumors, and then interrupt the nutrient supply and restrict the tumor metastasis." (PMID 40323152, 2025). "Besides, hypoxic tumor microenvironments stabilize HIF-1α/2α to upregulate drug efflux pumps (ABCB1/MRP1), while metabolic reprogramming through enhanced glutaminolysis and lipid metabolism supports redox homeostasis." (PMID 40771926, 2025).